EPB41L1 (erythrocyte membrane protein band 4.1 like 1)
Description:
May function to confer stability and plasticity to neuronal membrane via multiple interactions, including the spectrin-actin-based cytoskeleton, integral membrane channels and membrane-associated guanylate kinases.
Synonyms: 4.1N; KIAA0338; MRD11
Tractability: Antibody: its Gene Ontology location is reachable by antibodies, with high confidence; the Human Protein Atlas places it where antibodies can reach. PROTAC: ubiquitination databases record sites on it; its protein half-life has been measured.
Gene: Protein-coding gene on chromosome 20 (36,091,504 to 36,232,799, forward strand). Ensembl gene ENSG00000088367.
Subcellular location: Cytoplasm, cytoskeleton
Subcellular location (Human Protein Atlas): Plasma membrane
Pathways (Reactome):
Neuronal System: Neurexins and neuroligins; Trafficking of AMPA receptors
Sensory Perception: Sensory processing of sound by inner hair cells of the cochlea; Sensory processing of sound by outer hair cells of the cochlea
Gene Ontology:
Molecular function: protein binding; actin binding; cytoskeletal protein binding; structural molecule activity
Biological process: actomyosin structure organization; cortical actin cytoskeleton organization
Cellular component: plasma membrane; cytoskeleton; cytosol
Genetic constraint (gnomAD): Loss-of-function variants: 29 observed, 102.51 expected, observed/expected ratio (o/e) 0.28, 90% interval 0.21 to 0.39. The synonymous counts are far from expectation, so gnomAD's model fits this gene poorly and the ratio says little. Missense variants: 812 observed, 1,218.3 expected, observed/expected ratio (o/e) 0.67, 90% interval 0.63 to 0.71. Synonymous variants: 383 observed, 482.24 expected, observed/expected ratio (o/e) 0.79, 90% interval 0.73 to 0.86.
Gene-disease validity (ClinGen):
ClinGen rates the evidence that EPB41L1 causes each of these diseases.
complex neurodevelopmental disorder (autosomal dominant): Limited. A disorder that involves more than one phenotype associated with the central nervous system, including but not limited to intellectual disability, autism, and seizures (epilepsy).
Homologues: Orthologues: chimpanzee EPB41L1 (99% identical), macaque EPB41L1 (99% identical), guinea pig EPB41L1 (97% identical), dog EPB41L1 (97% identical), rabbit EPB41L1 (96% identical), mouse Epb41l1 (95% identical), rat Epb41l1 (91% identical), tropical clawed frog epb41l1 (64% identical), Drosophila melanogaster cora (33% identical), Caenorhabditis elegans frm-1 (32% identical), Drosophila melanogaster yrt (21% identical), Drosophila melanogaster Frmd5 (19% identical), and 3 more. Paralogues in human: EPB41L3 (48% identical), EPB41L2 (43% identical), EPB41 (40% identical), EPB41L4B (22% identical), EPB41L5 (21% identical), FRMD5 (20% identical), FRMD3 (19% identical), EPB41L4A (18% identical), FRMD6 (14% identical), MYLIP (12% identical).
Diseases named in the same sentence as EPB41L1 in open-access papers:
EPB41L1 is named in the same sentence as 14 diseases in open-access papers, as found by Europe PMC text mining. Sharing a sentence is not in itself a finding about the gene and the disease. The quoted sentences say what the papers report.
Intellectual disability (4 papers, 2014 to 2023). "Mutations in EPB41L1 disrupt glutamatergic systems in nonsyndromic intellectual disability, highlighting the role of regulating postsynaptic receptors in neuronal maintenance." (PMID 36799927, 2023). "Interestingly, EPB41L1 is associated with mental retardation, deafness autosomal dominant 11 and autosomal dominant non-syndromic intellectual disability." (PMID 31323926, 2019).
prostate carcinoma (3 papers, 2010 to 2021). A carcinoma that arises from epithelial cells of the prostate gland. "Previously, EPB41L1 was reported to significantly downregulate in prostate cancer tissues and be associated with biochemical recurrence." (PMID 34895055, 2021). "We also measured the EPB41L1 mRNA expression in blood samples from prostate cancer and cells and found a significant decrease of EPB41L1 mRNA level (P < 0.01)." (PMID 34895055, 2021). "Although it remains unclear, disruption of normal EPB41L1 expression may play an important role in disorganised cell and tissue structures associated with higher grade prostate cancer, and thus link its deregulation to prostate cancer progression and prognosis." (PMID 31835700, 2019). "Therefore, we suggest that miR-1255b-5p promotes prostate cancer cell proliferation, migration, and invasion through regulating EPB41L1." (PMID 34895055, 2021). "miR-1255b-5p promotes progression of prostate cancer via EPB41L1." (PMID 34895055, 2021). "Expression of EPB41L1 has been observed to be lower in prostate cancer compared to normal cells." (PMID 31835700, 2019).
breast carcinoma (1 paper, 2019). "Furthermore, reduced expression of EPB41L1 plays an important role in recurrence and has been associated with highly metastatic lung and breast cancer." (PMID 31835700, 2019).
gastric cancer (1 paper, 2019). A primary or metastatic malignant neoplasm involving the stomach. "EPB41L1 was also shown to be differentially expressed in gastric cancer." (PMID 31835700, 2019).
melanoma (1 paper, 2017). A malignant, usually aggressive tumor composed of atypical, neoplastic melanocytes. "Interestingly, this TGF-β activity also correlated with expression of an experimentally validated 6-gene “metagene” (VAV2, CORO1A, EPB41L1, CCT4, FRAP1, GJB3) reflecting integrin β1 activity, further supporting a link between integrin activity and TGF-β activity in human melanoma." (PMID 28448494, 2017).
cancer (7 papers, 2010 to 2025). A tumor composed of atypical neoplastic, often pleomorphic cells that invade other tissues. "Loss of EPB41L1 expression is reported in multiple cancer types and may play an important role in metastasis." (PMID 39931577, 2024). "EPB41L1 gene (erythrocyte membrane protein band 4.1 like 1) encodes the protein 4.1N, a member of 4.1 family, playing a vital role in cell adhesion and migration, which is associated with the malignant progression of various human cancers." (PMID 32760223, 2020). "Notably, seven UReg genes (GALNT14, KIAA0040, EPB41L1, ZNF469, BLNK, AK7, and WSCD1) are associated with the progression of various cancers in humans." (PMID 40241800, 2025). "The expression of EPB41L1 was decreased moderately, but significantly in cancer tissues." (PMID 20860828, 2010). "Research on the EPB41L1 gene's role in cancer cell migration and invasion is currently limited, but preliminary data suggest that changes in EPB41L1 may affect cytoskeletal remodeling, influencing the mobility of cancer cells." (PMID 40181462, 2025). "Our work shows that EPB41L1 and its co-expressed gene APP are coordinated to regulated cancer cell adhesion, which can increase the incidence of cancer cell metastasis and tumor invasion and lead to higher mortality in KIRC patients." (PMID 32760223, 2020). "Further analysis suggested that EPB41L1 and amyloid beta precursor protein (APP) were coordinated to regulated cancer cell adhesion, thereby increasing the incidence of cancer cell metastasis and tumor invasion." (PMID 32760223, 2020). "EPB41L1 and EPB41L3 were significantly downregulated and EPB41L4B was upregulated in cancer tissues." (PMID 20860828, 2010). "To further prove the specificity of EPB41L1 in KIRC, we integrated various clinic factors of KIRC samples in the TCGA database, for example, cancer stages, tumor grade, KIRC subtype, nodal metastasis status, patients’ gender, and age, and to compare the transcription levels of EPB41L1 in each group." (PMID 32760223, 2020). "The cooperative regulation of EPB41L1 and APP in cancer cells may indicate a special adhesion mechanism that can synchronize increased cell adhesion based on regulating cell adhesion-related pathway." (PMID 32760223, 2020). "In a similar fashion, EPB41L1 expression was on average lower in ERG-high than ERG-low cancers, but in this case the difference was not statistically significant." (PMID 20860828, 2010).
tumor (6 papers, 2019 to 2026). "Our study also revealed that the differential expression of GPR137 expression and EPB41L1 is associated with tumours of Gleason scores 3 + 4 = 7 and 8, respectively." (PMID 31835700, 2019). "EPB41L1-5 is known to maintain cell morphology and signal transduction, with evidence suggesting it can inhibit tumor progression." (PMID 41636170, 2026). "We previously identified that 4.1N/EPB41L1 acts as a tumor suppressor and is reduced in NSCLC patients." (PMID 35795202, 2022). "Then, we used qPCR to measure the miR-454-3p and 4.1N/EPB41L1 mRNA expressions in 37 NSCLC tissues and 31 tumor-adjacent tissues." (PMID 35795202, 2022). "Interestingly, eight among the overlapped hypermethylated genes (WT1, PAX6, GNAS, EPB41L1, CSMD1, CPEB1, RERG, and SMAD6) were previously reported to exhibit tumor suppressive functions." (PMID 34462486, 2021).
infection (2 papers, 2018 to 2021). The state of being infected such as from the introduction of a foreign agent such as serum, vaccine, antigenic substance or organism. "For instance, the proteins FMNL3, EPB41L1, SSH2, CORO1B and ARPC2 are detected only in E. ruminantium-infected cells, while in FSCN1 and GC, proteins are under-expressed or inhibited by infection." (PMID 34073568, 2021).
EPB41L1 also shares sentences with these, for which no sentence is quoted: cardiovascular diseases (1 paper); deafness autosomal dominant 11 (1); depression (1); facial clefting (1); neurodegenerative disease (1); prostate adenocarcinoma (1).